MDFIC2 (MyoD family inhibitor domain containing 2)
Gene: Protein-coding gene on chromosome 3 (70,194,479 to 70,312,638, reverse strand). Ensembl gene ENSG00000242120.
Gene Ontology:
Biological process: negative regulation of DNA-templated transcription; regulation of JNK cascade; regulation of Wnt signaling pathway; regulation of gene expression
Cellular component: nucleus
Homologues: Orthologues: chimpanzee MDFIC2 (99% identical), macaque MDFIC2 (97% identical), rabbit MDFIC2 (92% identical), dog MDFIC2 (90% identical), guinea pig MDFIC2 (86% identical), pig MDFIC2 (86% identical), rat Mdfic2 (85% identical), mouse Mdfic2 (81% identical), tropical clawed frog MDFIC2 (39% identical), zebrafish mdfic2 (28% identical). Paralogues in human: MDFIC (24% identical), MDFI (20% identical).
Diseases named in the same sentence as MDFIC2 in open-access papers:
MDFIC2 is named in the same sentence as 1 disease in open-access papers, as found by Europe PMC text mining. Sharing a sentence is not in itself a finding about the gene and the disease. The quoted sentences say what the papers report.
gestational diabetes (1 paper, 2025). Carbohydrate intolerance first diagnosed during pregnancy. "In Japanese populations, the gestational-diabetes-related loci include adiponectin (ADIPOQ), CDKN2A/2B, signal sequence receptor subunit 1-Ras-responsive element binding protein 1 (SSR1-RREB1), and MyoD family inhibitor domain-containing 2 (MDFIC2)." (PMID 40650275, 2025).